SF3B4 (splicing factor 3b subunit 4)
Diseases named in the same sentence as SF3B4 in open-access papers (continued):
Sharing a sentence is not in itself a finding about the gene and the disease.
esophageal squamous cell carcinoma (3 papers, 2022 to 2023). Esophageal squamous cell carcinoma (ESCC) is a type of esophageal carcinoma (EC) that can affect any part of the esophagus, but is usually located in the upper or middle third. "SF3B4 has been testified as an oncogene in esophageal squamous cell carcinoma." (PMID 35030977, 2022). "Additionally, SF3B4 has been reported to function as an oncogene in esophageal squamous cell carcinoma (ESCC)." (PMID 37875914, 2023).
immune deficiency (3 papers, 2020 to 2023). "In previous studies, SF3b4 was reported to participate in the regulation of the cell cycle, cell differentiation, and the mutation or deletion of the SF3b4 gene, resulting in immunodeficiency and tumorigenesis." (PMID 32276369, 2020). "SF3B4 is a subunit of the U2 small nuclear ribonucleoprotein that plays a crucial role in the splicing process, cell cycle regulation, cell differentiation, and immune deficiency-related activities." (PMID 37899451, 2023).
liver cancer (3 papers, 2020 to 2024). An epithelial or non-epithelial malignant neoplasm that arises from the liver. "We explored the protein expression of SF3B4 in liver cancer tissues using the Human Protein Atlas database." (PMID 37899451, 2023). "Approximately 83% of the liver cancer tissues showed positive expression of SF3B4." (PMID 37899451, 2023).
lung adenocarcinoma (2 papers, 2024). A carcinoma that arises from the lung and is characterized by the presence of malignant glandular epithelial cells. "Aberrant expression of splicing factors, including SF3B4, plays a vital role in lung adenocarcinoma (LUAD)." (PMID 38168564, 2024).
renal carcinoma (2 papers, 2023). A carcinoma arising from the epithelium of the renal parenchyma or the renal pelvis. "We then attempted to analyze this transcriptome sequencing dataset by combining the number of co-expression genes with SF3B4 in renal cancer and transcription factors from Uniprot database." (PMID 36639679, 2023).
asthma (1 paper, 2021). "Also, in the context of development of severe asthma, KEGG enrichment of the spliceosome (mRNAs; SF3A1, SNRPE, SF3B4) has been observed." (PMID 34068174, 2021).
cervical squamous cell carcinoma (1 paper, 2022). A squamous cell carcinoma arising from the cervical epithelium. "In this study, we found that splicing factor 3b subunit 4 (SF3B4) was highly expressed in CC by bioinformatics analysis using cervical squamous cell carcinoma and endocervical adenocarcinoma (CESC) data from The Cancer Genome Atlas (TCGA)." (PMID 35853859, 2022).
chronic hepatitis (1 paper, 2023). An active inflammatory process affecting the liver for more than six months. "An enzyme-linked immunosorbent assay (ELISA) was used to detect SF3B4 levels in plasma samples obtained from healthy controls (HCs) and patients with chronic hepatitis, liver cirrhosis, and HCC." (PMID 37899451, 2023).
clear cell renal cell carcinoma (1 paper, 2023). "However, the role of SF3B4 and underlying mechanisms in clear cell renal cell carcinoma (ccRCC) remain obscure." (PMID 36639679, 2023).
colorectal cancer (1 paper, 2023). A primary or metastatic malignant neoplasm that affects the colon or rectum. "Moreover, 3/4 driver-downregulated genes showed at least weak evidence of TSG role in the matched tissue (MED12 in brain, SF3B4 in breast, and CBLB in colorectal cancer), with the remaining 1 gene being classified as CGC TSG (CLTC)." (PMID 36625266, 2023).
non-small cell lung carcinoma (1 paper, 2023). A group of at least three distinct histological types of lung cancer, including non-small cell squamous cell carcinoma, adenocarcinoma, and large cell carcinoma. "SF3B4 is also closely related to the growth of non-small cell lung cancer cells." (PMID 36639679, 2023).
skin cancer (1 paper, 2024). "Per standard deviation increase in genetically predicted levels of protein, the OR of skin cancer ranged from 0.44 (95% CI = 0.28–0.69) for splicing factor 3B subunit 4 (SF3B4) to 1.50 (95% CI = 1.18–1.91) for Syntaxin-8 (STX8)." (PMID 39035989, 2024). "PTGES2, RNASET2, SF3B4, and STX8 showed significant associations with skin cancer after FDR correction." (PMID 39035989, 2024). "Interestingly, PTGES2, RNASET2, SF3B4, and STX8, associated with skin cancer risk, were also significantly associated with NMSC and BCC risks." (PMID 39035989, 2024). "Furthermore, prostaglandin E synthase 2 (PTGES2), ribonuclease T2 (RNASET2), SF3B4, and STX8 were significantly associated with skin cancer risk after FDR correction for multiple testing (FDR <0.05)." (PMID 39035989, 2024).
cancer (19 papers, 2019 to 2026). A tumor composed of atypical neoplastic, often pleomorphic cells that invade other tissues. "Next, we assessed the association between SF3B4 expression and prognosis among 10 different cancer types." (PMID 37899451, 2023). "Recent studies of SF3b4 homologs in different species across evolution will facilitate a better understanding of human diseases caused by the malfunction of SF3b4, such as Nager syndrome (NS) and cancer, in the future." (PMID 32083075, 2020). "In addition to known cancer-associated variants, we identified P/LP variants in the novel candidate cancer genes SF3B4, FMN2, and MMP13 (class 4)." (PMID 37377903, 2023). "Our study reveals a more complex picture in cancer, where chromosomal gains containing various splicing factors (1q gain: SF3B4, PRPF3, 2q gain: CWC22, SF3B1) and other NMD-related genes are associated with reduced NMD efficiency." (PMID 41023738, 2025). "It is shown that SF3B4 is strongly expressed in patients cross cancer types and the expression level is correlated with their survival." (PMID 41294857, 2025). "Among the 33 different cancer types, SF3B4 was significantly upregulated in tumor tissues compared with that in non-tumor tissues in 10 cancer types, including LIHC." (PMID 37899451, 2023). "In recent years, more and more research has been conducted on SF3b4-related diseases such as Nagel syndrome and cancer." (PMID 36639679, 2023). "Next, we examined SF3B4 expression in 53 pairs of ccRCC tissues and their adjacent non-carcinoma tissues and confirmed a significant increase in SF3B4 mRNA and protein levels in ccRCC tissues." (PMID 36639679, 2023). "Loss-of-function SF3B4 mutations in the germline lead to acrofacial dysostosis syndromes, including Nager/Rodriguez syndromes, and RNA-seq of mutated chondrocytes detected many splicing alterations, which may yield suitable reporter 3′ss for future testing of cancer variants." (PMID 32664474, 2020). "SF3B4 has been reported as a poor prognosis marker in various cancers." (PMID 40323145, 2025). "To explore whether SF3B4 is involved in the development of ccRCC, we first analyzed its mRNA level in the samples in the pan-cancer database of TCGA and found that SF3B4 was universally upregulated in a variety of tumors, including ccRCC." (PMID 36639679, 2023). "Importantly, SF3B4 was overexpressed in various cancers by pan-cancer analysis, indicating that SF3B4 is involved in the development and progression of human cancers." (PMID 35210412, 2022). "The distinct roles of SF3b4 in different cancer cells need further investigation." (PMID 32083075, 2020). "We find that physiochemically non-conservative residue substitutions in cancer mutation sites and anti-cancer drug binding site, as well as the lack of proline-rich motifs at the C-terminus of SF3b4, discriminate these fungi and pathogens from the rest of eukaryotes." (PMID 35082828, 2021). "Other studies have shown that SNRPE and SF3B4 could develop a new therapeutic agent in cancer." (PMID 33101358, 2020). "SRSF3 acts as an inhibitory regulator of SF3B4 that affects the activity and function of dendritic cells via the SRSF3-pyruvate kinase M2 pathway, which is crucial for cancer cell migration and immune killing." (PMID 37899451, 2023). "For example, we recently published that knockdown of SF3B4 induces reduction of FL TERT in NSCLC cells resulting in decreased telomerase activity, cell viability, and proliferation of cancer cells." (PMID 37531400, 2023). "The pan-cancer analysis results suggest that the eight hub genes (TXNRD1, TUBG1, SF3B4, PPM1G, PIGU, NDRG1, GRPEL2, and EZH2) were differentially expressed in gastrointestinal tumors." (PMID 36686830, 2022). "The involved splicing factor SF3B4 was found to be a survival-related gene in ESCC and is presumed to regulate AS in multiple cancers." (PMID 33563334, 2021). "Splicing factor 3b subunit 4 (SF3B4) is frequently overexpressed in HCC samples, where it promotes cancer development." (PMID 33266506, 2020).
cancer (continued). "We note this narrower CNA segment does not include the MDM4 oncogene, which is located at 1q32.1, thus other genes must be driving this recurrent genetic change in CNA-PC86, with possible candidates being known cancer genes BCL9 (1q21.2), ARNT (1q21.3), SETDB1 (1q21.3), or SF3B4 (1q21.2)." (PMID 41023738, 2025). "Initially, we examined SF3B4 expression in tumor and non-tumor tissues using the pan-cancer database, TCGA." (PMID 37899451, 2023). "Overexpressing SF3B4 resulted in a mis-splicing of Kruppel-like factor 4 (KLF4), a tumor suppressor-encoding gene, into a non-functional transcript in cancer cells, and thus promoting tumorigenesis in HCC." (PMID 33563334, 2021). "In humans, overexpressing SF3b4 resulted in a mis-splicing of Kruppel-like factor 4 (KLF4), a tumor suppressor-encoding gene, into a non-functional transcript in cancer cells, and thus promoting tumorigenesis in HCC." (PMID 32083075, 2020). "The altered expression level of hub SFs has been reported in multiple types of cancer, such as YBX1, SART1, SNRPE, and SF3B4." (PMID 33101358, 2020). "Conversely, when SF3B4 was knocked down in non-cancerous cells (human bronchial epithelial cells, HBECs) it did not reduce viability or proliferation of cells proposing a new approach for cancer cell specific therapy." (PMID 37531400, 2023).
tumor (15 papers, 2019 to 2026). "SF3B4 may be associated with tumor immune infiltration in HCC, and EV-SF3B4 shows potential as a novel non-invasive diagnostic biomarker of HCC." (PMID 37899451, 2023). "In vivo, SF3B4 silencing significantly inhibited tumor growth and reduced SREBF1 expression in xenograft models." (PMID 42255207, 2026). "After 3 weeks, we found dramatic decreases in tumor size and weights from the mice-bearing tumors derived from SF3B4 knockdown cells compared to the control." (PMID 38168564, 2024). "The TIMER database was used to verify the correlation between SF3B4 expression and tumor immune cell infiltration levels in HCC." (PMID 37899451, 2023). "More importantly, stable knockdown of KLF16 largely attenuated the promoting effect of SF3B4 overexpression on tumor growth." (PMID 36639679, 2023). "The Tumor Immune Estimation Resource database reconfirmed the correlation between SF3B4 expression and immune cell infiltration in HCC." (PMID 37899451, 2023). "Meanwhile, we established a mouse xenograft tumor model to prove that the growth of subcutaneous tumors was much slower when SF3B4 was knocked down." (PMID 35210412, 2022). "SF3B4 knockdown decreased the tumor size and tumor weight significantly, indicating that knockdown of SF3B4 expression efficiently reduced CC cell tumorigenesis in vivo." (PMID 35853859, 2022). "Six AS events regulated by SF3B4 in tumor samples overlapped with the top SF3B4 regulated AS events in ESCC." (PMID 33563334, 2021). "Six overlapping AS events regulated by SF3B4 in tumor samples were finally verified, including 1 SE event (ATP2B4) and 5 RI events in 4 genes (SRSF5, PHF6, SNHG12, KIAA1217)." (PMID 33563334, 2021). "Meanwhile, we proved that the SF3B4 knockdown slowed tumor growth in a mouse model." (PMID 38168564, 2024). "SF3B4 is highly expressed in MDSCs in the tumor microenvironment, and the aberrant expression of SF3B4 and MDSC markers may help predict poor prognosis in patients with HCC." (PMID 37899451, 2023). "Furthermore, SF3B4 expression was positively correlated with tumor purity, regulatory T cells, and MDSCs and negatively correlated with NK cells." (PMID 37899451, 2023). "Therefore, we investigated the relationship between SF3B4 and immune cells in the tumor microenvironment." (PMID 37899451, 2023). "Moreover, decreased expression of RAD52 partially counteracted the tumor-promoting effect of SF3B4 overexpression." (PMID 35210412, 2022). "To validate the regulatory role of SF3B4 on AS events in tumor samples, we have downloaded two RNA-seq datasets with SF3B4 knockdown, and calculated the inclusive levels of AS events with IncLevelDifference between control shRNA and SF3B4 knockdown." (PMID 33563334, 2021). "In HCC, tumor genes such as procollagen-lysine, 2-oxoglutarate 5-dioxygenase 3 (PLOD3), and splicing factor 3b subunit 4 (SF3B4) are overexpressed in HCC tumor tissues compared with adjacent tissues, and knocking down their expression levels can effective suppress tumor invasion." (PMID 31156698, 2019). "ENAH's activity is modulated by the RBP splicing factor 3b subunit 4 (SF3B4), activating Notch signaling and driving tumor progression." (PMID 40271197, 2025). "The immunohistochemistry (IHC) results demonstrated that DYNC1H1, GTPBP4, PRKDC, RBM19, SF3B4, SPATS2 and TAF9 were significantly increased in HCC tumor cells compared to normal hepatocytes." (PMID 33411682, 2020). "Among six SFs, the level of SF3B4 in ACC cases with the tumor stage III and the level of PRCC and SF3B4 in ACC cases with stage IV were statistically different from those in stage I, which is consistent with the results from the GEPIA database." (PMID 33101358, 2020). "Consequently, SF3B4 was highly expressed in the nuclei of tumor tissues compared with that in non-tumor tissues." (PMID 37899451, 2023). "Similarly, we performed IHC analysis on non-tumor and tumor tissues from patients to confirm the expression of SF3B4." (PMID 37899451, 2023).
dysostosis (1 paper, 2020). A group of disorders in which the skeletal involvement is predominantly manifested as abnormalities of individual bones or in a group of bones. "By studying the heterozygous SF3b4 mutants, which are haploinsufficient, it was determined that SF3b4 is a causative factor for NS, an acrofacial dysostosis that causes upper limb and facial-mandibular defects." (PMID 32083075, 2020).
infection (1 paper, 2013). The state of being infected such as from the introduction of a foreign agent such as serum, vaccine, antigenic substance or organism. "At early infection stage (at 24 h post infection), genes contributing to the nuclear transport like KPNA2 and KPNB1, RNA splicing gene SF3B4 were down-regulated compared with the normal control." (PMID 23451031, 2013).
SF3B4 also shares sentences with these, for which no sentence is quoted: Cerebro-costo-mandibular syndrome (3 papers); Cirrhosis (2); craniofacial microsomia (2); mandibulofacial dysostosis (2); microcephaly (2); Burn–McKeown syndrome (1); cleft palate (1); colon cancer (1); endocervical adenocarcinoma (1); esophageal cancer (1); gastrointestinal tumors (1); immunodeficiency (1); leukemia (1); liver cirrhosis (1); Macrocephaly (1); Micrognathia (1); Nonsyndromic Orofacial Cleft (1); ocular hypertelorism (1); retinitis pigmentosa (1); thrombocytopenia-absent radius syndrome (1); Treacher-Collins syndrome (1).